RN7SL549P (RNA, 7SL, cytoplasmic 549, pseudogene)
Gene: Miscellaneous RNA gene on chromosome 7 (100,906,291 to 100,906,572, reverse strand). Ensembl gene ENSG00000239825.
Homologues: Orthologues: chimpanzee Metazoa_SRP (99% identical). Paralogues in human: RN7SL2 (84% identical), RN7SL1 (83% identical), RN7SL3 (83% identical), RN7SL186P (82% identical), RN7SL386P (82% identical), RN7SL45P (81% identical), RN7SL408P (80% identical), RN7SL589P (80% identical), RN7SL615P (80% identical), Metazoa_SRP (80% identical), Metazoa_SRP (79% identical), RN7SL126P (79% identical), and 705 more.